USP19 (ubiquitin specific peptidase 19)
Diseases named in the same sentence as USP19 in open-access papers (continued):
Sharing a sentence is not in itself a finding about the gene and the disease.
cancer (continued). "USP19 not only regulates cancer cells but also performs various functions within cells, such as differentiation of muscle cells, viral immune response, autophagy, macrophage polarization, cell cycle regulation, chromosome stabilization, and repair of DNA damage." (PMID 34201062, 2021). "The results that USP19 is deep deleted or down-regulated in various human cancers further strengthen the possibility that USP19 might function as a tumor suppresser by facilitating DNA damage repair and protecting chromosome stability." (PMID 27517492, 2017). "Altogether, this strongly suggests that constitutive activation of the Ras signalling pathway may figure among mechanisms explaining altered USP19 function and p27Kip1 levels in cancer cells." (PMID 21264218, 2011). "To explore whether this role of USP19 extends to other cellular systems, we tested the effects of silencing of USP19 in several human prostate and breast models, including carcinoma cell lines." (PMID 21264218, 2011). "In addition, USP19, a typical protein in the family of ubiquitin-specific peptidases, is involved in key oncogenes or other proteins involved in tumor progression and is a potential pro- or anti-cancer factor." (PMID 40280943, 2025). "Currently, the factors upstream and downstream of USP19 that affect cancer cells remain unclear." (PMID 40280943, 2025). "Therefore, anti-tumor or pro-tumor effects mediated by USP19-CY may differ depending on cancer subtype." (PMID 36646950, 2023). "Our molecular mechanism study revealed that USP19 has a role as a co-repressor in the transcriptional repression of RAR via the stabilization of CORO2A by its DUB activity, and suggests the possibility that USP19 may be a potent target for anti-cancer and metabolic diseases." (PMID 27129179, 2016). "The expression of PTK2, USP19, LAMC2, VEGFA, EPHA2, and MMP2 varies greatly among different cancer samples and has relatively high expression." (PMID 38694917, 2024). "The identification of herboxidiene as a specific modulator of USP19 splicing and its concomitant inhibitory effects on TGF-β/SMAD signaling and cancer migration further validates the opposing roles of USP19-ER and USP19-CY in these processed." (PMID 36646950, 2023). "USP19 promotes tumor formation in gastric cancer by upregulating MMP2 and MMP9 involved in cancer migration and invasion and regulates the growth of Ewing sarcoma by acting as a DUB of the chimeric transcription factor EWS-FLI1." (PMID 34201062, 2021). "Moreover, studies using artificial intelligence have identified genes like Ubiquitin carboxyl-terminal hydrolase 19 (USP19) and RPL23 as crucial for predicting cancer recurrence." (PMID 39891297, 2025). "However, whether the differential localization of USP19 impacts TGF-β signaling and its role in TGF-β-induced EMT, cell migration and invasion of cancer cells remain unclear." (PMID 36646950, 2023).
tumor (18 papers, 2017 to 2025). "In the last couple of years, increasing evidence has begun to demonstrate that USP19 is associated with tumor progression and that it represents a novel prognostic factor for the outcome of several malignant diseases." (PMID 35646888, 2022). "In this study, we demonstrated that TIPE3 promotes autophagy in CRC cells and tumor-bearing mice via USP19/Beclin1 and induces macrophage M2 polarization, thus strengthening the resistance of tumor cells to L-OHP." (PMID 40280943, 2025). "In vivo experiments in mice suggested that TIPE3 inhibited apoptosis of tumor cells and promoted macrophage M2-type polarization in tumor tissues by up-regulating the protein expression of USP19." (PMID 40280943, 2025). "The catalytic activity of USP19 plays a key role in controlling tumor cell proliferation in tissues from patients with breast cancer." (PMID 40280943, 2025). "The colony formation and tumor growth study in xenograft assess USP19 affects the GBM sensitive to TMZ was performed by T98G, LN18, U251, and U87 cell lines." (PMID 38644551, 2024). "It was clear that tumour development rates in the USP19 overexpression groups were much slower than those of the control groups, and tumour weights were also significantly reduced." (PMID 37700495, 2023). "The idea that USP19 operates as a potential tumour suppressor gene in TNBC was confirmed by FCM measurement of apoptosis." (PMID 37700495, 2023). "Tumour samples from each group were stained for Ki67, demonstrating that USP19 overexpression tumour‐bearing mice had much lower cell proliferation marker Ki67." (PMID 37700495, 2023). "Consistent with in vitro experiments, overexpression of endogenous USP19 markedly attenuated both the tumour size and weight in vivo." (PMID 37700495, 2023). "BC cells that had been transduced with USP19‐targeting plasmid were injected into the flank of 5‐weeks old female nude mice to further demonstrate the tumour suppression role of USP19 in vivo." (PMID 37700495, 2023). "Our results revealed that the levels of GRP78, ATF4, CHOP, p‐IRE, and XBP1 expression were increased in mouse tumour tissue overexpressing USP19, indicating an increased ER stress parallel to the expression of USP19 in TNBC tumorigenesis." (PMID 37700495, 2023). "They validated their results using in vivo models and observed that USP19 downregulation promoted tumor growth in a xenograft model." (PMID 35646888, 2022). "Gierisch and collaborators demonstrated that this protein, which maintains tumor cells survival, is regulated by USP19 in a post translational manner, and dependent on its catalytic activity." (PMID 35646888, 2022). "Using in vivo experiments, the authors demonstrated that tumor growth was delayed when USP19 levels were reduced." (PMID 35646888, 2022). "More importantly, we demonstrated that USP19 catalytic activity is important for the control of tumor cell migration and invasion, and that its molecular mechanism of action involves LRP6, a Wnt co-receptor." (PMID 33714979, 2021). "USP19 depletion inhibits tumor foci formation in vivo, as evaluated by human DNA quantification (left) and metastatic load quantification in Hematoxylin & Eosin-stained lung sections (right, and Supp." (PMID 33714979, 2021). "The decreased EWS-FLI1 protein level upon USP19 depletion abrogated long term cell growth and delayed tumor growth in mouse xenograft experiments." (PMID 30700749, 2019). "Most importantly, we also observed a significant tumor growth delay upon USP19 knockdown in an in vivo xenograft model." (PMID 30700749, 2019). "In addition, consistent with the results of the experiments in LoVo and SW480 cells, TIPE3 also increased the protein expression level of USP19 in mouse tumor tissues." (PMID 40280943, 2025). "Depletion of USP19 dramatically sensitized T98G cells to TMZ in flank tumor models." (PMID 38644551, 2024). "The pace of mouse tumour development was considerably reduced by targeting USP19." (PMID 37700495, 2023).
tumor (continued). "Furthermore, the authors of this study also showed that USP19 depletion decreased tumor growth and metastasis in vivo." (PMID 36646950, 2023). "In vivo experiments showed that USP19 silencing reduces tumorigenicity and delays tumor onset and growth, and the opposite was observed upon wild type USP19 overexpression (but not when overexpressing a catalytically dead mutant, or a cytoplasmic version of USP19)." (PMID 35646888, 2022). "On the contrary, overexpression of wild-type USP19, but not its catalytically deficient mutant version, promoted tumor growth." (PMID 33714979, 2021). "Our results demonstrated that USP19 expression correlates with tumor growth and invasion." (PMID 33714979, 2021). "Second, we analyzed USP19’s role in the regulation of tumor cell lung colonization." (PMID 33714979, 2021). "To validate USP19 function as a positive regulator of migration and invasion, we performed a series of in vitro and in vivo experiments analyzing USP19’s role in colonization and tumor formation." (PMID 33714979, 2021). "Collectively, our results indicate that USP19 knockdown inhibits tumor cell invasion in vitro." (PMID 33714979, 2021). "Altogether, we concluded that USP19 is important for in vivo colonization and tumor growth." (PMID 33714979, 2021). "USP19 inhibition subsequently resulted in decreased tumor cell growth in vitro and in vivo." (PMID 30700749, 2019). "Taken together, we could show that USP19 depletion significantly delays tumor cell growth also in vivo confirming our in vitro findings." (PMID 30700749, 2019). "Therefore, the same signaling pathway may exist between TIPE3 and USP19 to achieve oncogenic effects, thereby enhancing the resistance of tumor cells to chemotherapy drugs." (PMID 40280943, 2025). "Therefore, we decided to investigate the effect of USP19 depletion on tumor cell invasion." (PMID 33714979, 2021). "Moreover, the downregulation of USP19 promoted tumor growth in a xenograft model." (PMID 34439131, 2021). "Furthermore, the expression level of USP19 is commonly lower or deleted in several types of tumor." (PMID 27517492, 2017). "Furthermore, the USP19 gene is commonly deep deleted in several types of tumor samples." (PMID 27517492, 2017). "In summary, TIPE3 regulated the expression of cell cycle- and apoptosis-related proteins through the USP19/Beclin1-pathway, thus reducing the damaging effects of L-OHP on tumor cells." (PMID 40280943, 2025). "siUSP7, siUSP8, siUSP14 and siUSP19 lead to the largest reduction in TOM22, which means induction of mitophagy and anti-tumor effect, but USP8 and USP19 are low expressed in tumor." (PMID 40316942, 2025). "Several deubiquitination enzymes, such as CSN5, USP1, USP19, and STAMBPL1, prevent the ubiquitin degradation process of survivin and stabilize its expression, leading to tumor progression and therapeutic resistance 48-50." (PMID 38356707, 2024). "Here, we showed that USP19 binds to BAG6 and decreases BAG6 ubiquitination, which prevents BAG6 from being degraded in TNBC tumour tissue and BC cells." (PMID 37700495, 2023). "USP19, USP44, USP46, and USP53 has been revealed as potential tumor suppressor in KIRC in the previous study." (PMID 37259026, 2023). "Downregulation of USP19 levels resulted in a reduction of EWS-FLI1 levels, hence decreasing tumor cells growth and colony formation capability, whereas the opposite occurred upon USP19 (TM isoform) overexpression." (PMID 35646888, 2022). "Finally, we investigated whether USP19 depletion would affect tumor growth in mouse xenografts." (PMID 30700749, 2019). "Recovering the expression of the tumor suppressor, such as USP19, USP44, and USP53, also might reach the tumor-inhibited effect for this type of patient." (PMID 37259026, 2023). "In particular, it has been shown that USP19 plays both positive and negative roles in the onset and development of diverse neoplasms, in a tissue-specific manner." (PMID 35646888, 2022).
tumor (continued). "The role of genes RBM15B and USP19 may be important in BAP1 function and give further insight into the mechanism of BAP1 tumor suppression and additional targets for therapy." (PMID 30716094, 2019). "Depletion of USP19 was shown to decrease EWSR1-FLI1 expression levels, but neither the expression of wild-type of EWSR1 nor FLI1, and to reduce tumor growth in vitro and in vivo indicating a potential therapeutic value for USP19 inhibition." (PMID 31970591, 2019). "Moreover, USP19 (induced by TIPE3) triggers macrophage M2 polarization in the tumor microenvironment, inhibiting the immune response and affecting autophagy and apoptosis of tumor cells." (PMID 40280943, 2025).
heart disease (1 paper, 2020). "Although USP19 is expressed in the heart, the role of USP19 in the heart disease remains unknown." (PMID 32798288, 2020).
infection (1 paper, 2019). The state of being infected such as from the introduction of a foreign agent such as serum, vaccine, antigenic substance or organism. "Deficiency of USP19 increased serum cytokine levels after administration of poly(I:C) and LPS, and promoted inflammatory death caused by administration of poly(I:C) or LPS, or infection of Salmonella typhimurium." (PMID 31511519, 2019). "However, our results indicated that USP19-deficiency did not affect induction of downstream effector genes after infection with both RNA and DNA viruses or stimulation with TLR2 and TLR7/8 ligands in mouse primary immune cells." (PMID 31511519, 2019).
USP19 also shares sentences with these, for which no sentence is quoted: spinocerebellar ataxia (3 papers); adenoma (1); autism spectrum disorder (1); Cachexia (1); cervical squamous cell carcinoma (1); colon cancer (1); esophageal carcinoma (1); heart failure (1); Hereditary breast and ovarian cancer syndrome (1); hypertrophy (1); lymphoma (1); metabolic disease (1); metastatic disease (1); neurodegenerative disease (1); Spinocerebellar ataxia type 3 (1); stomach adenocarcinoma (1); triple-negative breast carcinoma (1); uveal melanoma (1).